LTBR (lymphotoxin beta receptor)
Diseases named in the same sentence as LTBR in open-access papers (continued):
Sharing a sentence is not in itself a finding about the gene and the disease.
cancer (continued). "Whilst the role of LTβR in immune regulation and inflammation has been well established, less is known about its implication in cancer, especially in terms of the relative contribution of classical versus alternative NF-κB activation." (PMID 39215104, 2024). "We investigated the expression of LTBR in normal cell line (293T) and cancer cell lines (SW480, Caco-2, SCC25, NH4) by employing qPCR." (PMID 39068665, 2024). "To gain a better understanding of LTβR signaling in cancer cells, we first performed mechanistic and functional analyses of LTβR activation in several cancer cell lines representing different tissues of origin." (PMID 39215104, 2024). "Finally, LTβR can activate NFκB and stimulate pro-inflammatory cytokine secretion, and the ability of LTβR to promote inflammatory cytokine secretion and tertiary lymphoid tissues may increase the risk of cancers in the liver and prostate." (PMID 37893069, 2023). "The role of active LTβR signaling in lymphocyte migration to lymph nodes makes it a therapeutic approach in inflammatory and infectious diseases, as well as cancer." (PMID 37176092, 2023). "Another role of LT networks, i.e., LTβR signaling, is involved in the progression of cancer by inhibiting the adaptive immune response of the host to cancer cells." (PMID 35454851, 2022). "It has been reported that the activation of LTβR by its ligand, LTα1β2, affects the development of several cancers by inhibiting the adaptive immune response of host cells." (PMID 35454851, 2022). "Nearly three decades of work has expanded the role of LTβR beyond the scope of lymphoid organ development and maintenance to include roles the in regulation of mucosal repair, cancer, inflammation and autoimmunity." (PMID 34335629, 2021). "Lymphotoxin beta receptor (LTβR) is a promising therapeutic target in autoimmune and infectious diseases as well as cancer." (PMID 34335629, 2021). "Here, we focus on the novel functions of LTβR signaling in lymphatic endothelial cells for migration of regulatory T cells (Tregs), and specific targeting of LTβR signaling for potential therapeutics in transplantation and cancer patient survival." (PMID 33805271, 2021). "Therapeutic strategies for inhibition or stimulation of LTβR signaling are currently in development for treatment of inflammatory and infectious diseases as well as cancer." (PMID 34335629, 2021). "However, since LTα-, LTβR-, and RORγt+ LTα-deficient mice all have abnormalities in the secondary lymphoid tissue formation, their susceptibility to chemically induced cancer may partially be associated with the delayed adaptive antitumor response." (PMID 33917839, 2021). "The CNV gain in the 43 kb region in 12p13.31 in 601covers the genes SCNN1A, LTBR and CD27 and CD27 overexpression has been found to be associated with the development of different cancers." (PMID 30975103, 2019). "Recently, targeting of LTβR-triggered signaling was proposed as a strategy in treatment of cancer resistant to PD-L1 blockade." (PMID 31878945, 2019). "With regard to LTβR, cytoplasmic expression was noted in CAFs, TILs and TAMs in all tissue samples while nuclear staining was observed in cancer cells in a very high percentage of cases (86.5%)." (PMID 31137630, 2019). "The LTβR signaling pathway plays an important role in inflammation-induced cancer processes, including the transformation from hepatitis to liver cancer, and prostate cancer occurrence and metastasis." (PMID 25369740, 2015). "LTβR is an upstream activator of NF-κB that can activate the canonical NF-κB pathway in a number of carcinomas." (PMID 25369740, 2015). "LIGHT (TNFSF14) binds to TNFRSF14 (HVEM) and LTβR on cancer cells, promoting apoptosis." (PMID 40564222, 2025).
cancer (continued). "To investigate the functional role of LTβR in tumors, we performed LTβR knockdown in cancer cells." (PMID 40883295, 2025). "Therefore, we sought to determine the role of LUBAC in LTβR-induced NF-κB activation in cancer cells." (PMID 39215104, 2024). "Together, we here identify LUBAC as a previously unrecognized crucial factor that determines the functional signaling output of LTβR activation, which could be exploited for cancer patient stratification and new therapeutic approaches." (PMID 39215104, 2024). "We next analyzed the impact of LTβR expression on patient survival in different cancer types." (PMID 39215104, 2024). "It was previously reported that LTβR signaling can promote cell death in certain cancer types." (PMID 39215104, 2024). "Independently thereof, our data shows that, in cancer cells, activation of LTβR induces secretion of pro-inflammatory cytokines known to be tumorigenic, and that this requires activation of the canonical NF-κB pathway which is, in turn, activated in a LUBAC- and linear-ubiquitin-dependent manner." (PMID 39215104, 2024). "Because of the biochemical and functional results we obtained in our study we were prompted to determine whether there could be a connection between LUBAC and LTβR in cancer." (PMID 39215104, 2024). "Notably, we identified LTBR as a potential target for cancer immunotherapy and a marker of immune infiltration and poor prognosis." (PMID 38175686, 2024). "We found that LTBR, which was highly expressed in H-CM, showed anti-cancer effects, and we identified the intracellular signaling patterns and hub proteins related to the enhanced anti-cancer effects." (PMID 35563525, 2022). "The precise peptide-targeting approach could be a potential cancer therapy, especially since many cancers have persistently active LTβR signaling." (PMID 33805271, 2021). "Our study also showed that LTβR rs10849448 (A>G) SNP is associated with NSCLC risk, with homozygosity for the alternative A allele being related to lower risk for NSCLC, a finding that correlates for the first time this variant with cancer risk." (PMID 34604057, 2021). "For boosting LTβR signaling, cholesterol sequestration or depletion from the plasma membrane reportedly prevented LTβR internalization and then activated LTβR-canonical NFκB signaling in lung epithelia to promote pro-inflammatory responses against cancer cells." (PMID 33805271, 2021). "This suggests that the downregulation of iNOS, TNFα and IFNγ in MAMs in our model may occur through a direct interaction between LTβ on cancer cells and the LTβR on MAMs." (PMID 27203741, 2016). "Alternatively, homotypic LTβ/LTβR interactions between cancer cells may alter their cytokine profiles, which may have an indirect effect on iNOS and inflammatory cytokines in MAMs." (PMID 27203741, 2016). "In parallel, the role of the LTβR signaling pathway in cancer has been recognized." (PMID 25369740, 2015). "Moreover, we highlighted the importance of N-glycosylated LTβR in regulating the Th17/Treg cell balance and suggested that LTβR could increase the sensitivity to the glycolysis inhibitors for cancer prevention, which in turn enhanced the therapy of LTβR." (PMID 40436857, 2025). "In addition, data from the Cancer Therapeutics Response Portal (CTRP) database of the Broad Institute indicate that LTβR expression is negatively correlated with the efficacy of certain anti-cancer drugs, including doxorubicin (topoisomerase II inhibitor) and nutlin-3a (MDM2 inhibitor)." (PMID 40883295, 2025). "However, we could not detect a reduction in cell viability or induction of cell death upon LTβR activation among the different cancer cell lines we tested." (PMID 39215104, 2024).
cancer (continued). "The low incidence of LTBR mutations in tumors shows that LTBR gene alterations may not significantly contribute to cancer development." (PMID 38175686, 2024). "CD8+ T cells were involved in the initial aggregation and reticular network formation of cancer-associated fibroblasts (CAFs), while B cells recruited via CXCL13 drove CAF proliferation and the expansion of TLS through lymphotoxin beta/lymphotoxin beta receptor (LTBR) crosstalk." (PMID 37419983, 2023). "However, some cancer cells were refractory to this anti-LTβR mAb treatment." (PMID 33805271, 2021). "Since LTβR and NF-κB appear simultaneously upregulated in BCa, and previous studies have indicated that LTβR acts as an upstream activator of NF-κB in numerous carcinoma cells, we explored the correlation between the two proteins in BCa tissues, using Pearson and Spearman’s rank correlation tests." (PMID 25369740, 2015). "Although these concepts are exciting, validating the relationship between LTβR, HOIP expression and LUBAC activity in preclinical models and in human cancers requires further investigation." (PMID 39215104, 2024). "Our results provide a direct link between the LUBAC and LTβR-induced activation of canonical NF-κB signaling and secretion of IL-8 and CCL20 by cancer cells." (PMID 39215104, 2024). "Concerning immune checkpoints, highly expressed TNFSF14 in Neutrophils, NK Cells, and Monocytes, BTLA in Treg Cells, Granulosa Cells, and B Cells, together with LTBR and TNFRSF14 in Cancer Cells, interact to help kill Cancer Cells." (PMID 36401283, 2022). "In addition, the published data regarding the clinical value of LTβR rs10849448 (A>G) refer to its association with individuals’ risk of undergoing tonsillectomy and juvenile idiopathic arthritis, while no data exist regarding its significance in cancer." (PMID 34604057, 2021). "In castration resistant prostate cancer, tumor infiltrating B-cells secrete lymphotoxin (LT) α:β which engages with LTβR on cancer cells and activates the STAT3 pathway to promote androgen-independent cancer cell growth." (PMID 30356678, 2018). "Of these genes, TNFRSF1A and TRADD were found to be upregulated since they work as the trigger molecules of the apoptotic cascade in cancer cells whereas antiapoptotic genes MCL-1 and LTBR were found to be downregulated." (PMID 20673323, 2010). "On the other hand, the most frequently down regulated AM genes are TGFBR2 (7/13 of cancer models), BAG3, CLU, LGALS1, LTBR, SGK (in 6/13)." (PMID 19402918, 2009). "The lymphotoxin β receptor (LTβR), a key activator of non-canonical NF-κB signaling, is expressed in various cells, including cancer cells." (PMID 40883295, 2025). "Analysis of cancer patient-derived RNA-sequencing data from public databases, revealed a strong correlation between decreased overall survival and the combination of high expression of both, HOIP and LTβR in HCC patients." (PMID 39215104, 2024). "In addition, decoy cell receptor 3 (DcR3) is a secreted factor identified in several different malignancies, such as cancers of the lung, colon, GI tract, and brain, that binds to LIGHT and blocks interaction of LTβR and LIGHT." (PMID 33805271, 2021).
cancer (continued). "Recent investigations in cancer therapy have demonstrated that LIGHT administered as a fusion protein restored blood vessel homeostasis in tumors in vivo, among others, through increased expression of contractile proteins such as SM α-actin in a LTβR-dependent manner." (PMID 34829747, 2021). "SLC11A1, TNFRSF1B, and LTBR have not yet been reported on prognostic factors in GBM, thus, suggestive of novel target candidates for cancer immunotherapy." (PMID 29721184, 2018). "Surprisingly, despite a clear activation of the non-canonical NF-κB pathway in the cancer cells tested, they did not secrete the chemokines CXCL12, CXCL13, CCL19 and CCL21, known to be induced as a consequence of activation of this signaling pathway upon LTβR stimulation of other cell types." (PMID 39215104, 2024).
infection (29 papers, 2008 to 2026). The state of being infected such as from the introduction of a foreign agent such as serum, vaccine, antigenic substance or organism. "Like in the Listeria model, mice treated with LTβR-Ig, or mice conditionally deficient in Ltbr in bone marrow MSCs, were significantly more susceptible to infection of HSV2, a pathogen that is also controlled by monocyte-mediated immunity." (PMID 36717247, 2023). "To characterize the cause of this susceptibility in LTβR−/− mice, we first assessed the parasite burden in T. gondii-infected WT and LTβR−/− animals during the acute phase of infection via quantitative realtime PCR (qRT-PCR)." (PMID 33753412, 2021). "Though Heat-iHSV induced a weaker Th1 response than HSV-1 infection, LTβR signaling deficiency still resulted in an enhanced Th1 response in the Heat-iHSV infection." (PMID 30531962, 2018). "While wild-type C57BL/6 and TNF-deficient mice presented signs of ischemic brain damage and vascular blood flow perturbations upon blood stage PbA infection, LTαβ and LTβR deficient mice displayed a normal MRI." (PMID 18612394, 2008). "We next characterized brain-sequestered leukocytes, in wild-type and TNF deficient mice with severe neurological symptoms after PbA infection and in LTβR or LTβ deficient mice at the same day after infection." (PMID 18612394, 2008). "Furthermore, the fact that LTβR-Ig treatment rescued the cortical demyelination observed in response to infection suggests that the meningeal ELAs are indeed pathogenic." (PMID 37983289, 2023). "Moreover, the infection of 16-week-old Ccl19-iEYFP Ltbrfl/fl mice (Dox off 8 wk) with C. rodentium revealed increased susceptibility of the mice when LTβR signaling was abrogated specifically in adult Ccl19-expressing FRCs." (PMID 35440118, 2022). "Importantly, the LTβR-pathway also plays an essential role for the defense against this pathogen, since LTβR-deficient mice were found to be highly susceptible to C. rodentium and to succumb rapidly upon infection." (PMID 27656182, 2016). "Notably, LTβR-deficient (LTβR-/-) mice exhibit severe defects in innate and adaptive immunity against various pathogens and succumb to Toxoplasma gondii infection." (PMID 40924438, 2025). "Another major LIGHT receptor, LTβR, has been demonstrated to play a pivotal role in the development of T-cell-mediated immunity against infection." (PMID 39768135, 2024). "Here, we have shown that the expression of genes within the TNFR and LTβR signaling pathways in the WP were modulated by STm infection." (PMID 36950118, 2023). "Infection of Salmonella in LTβR−/− mice demonstrates that organized lymph tissues are dispensable for the systemic infection of the host." (PMID 35722038, 2022). "Conversely, IL-6 expression in the serum is markedly increased in LTβR−/− mice compared to WT mice throughout the infection." (PMID 33753412, 2021). "In contrast, in LTβR−/− mice, IL-6 amounts rose significantly during the course of infection and were significantly higher on days 7 and 10 p.i. than those of WT mice." (PMID 33753412, 2021). "In infection models, LTβR−/− mice show pronounced defects in their immune response against Listeria monocytogenes, Mycobacterium tuberculosis, cytomegalovirus, lymphocytic choriomeningitis virus (LCMV), and Zika virus, as well as Toxoplasma gondii (T. gondii)." (PMID 33753412, 2021). "And while LTβR−/− animals do upregulate mGBP expression during the course of infection, they show significantly lower expression on day 10 p.i. than WT mice in all cases except for mGBP6/10." (PMID 33753412, 2021). "To add additional kinetic data RNA-seq data and cytokine levels in serum, we determined mRNA expression levels of cytokines in the lungs of infected WT and LTβR−/− mice at several time points after infection." (PMID 33753412, 2021).